TLR4 (toll like receptor 4)
Diseases named in the same sentence as TLR4 in open-access papers (continued):
Sharing a sentence is not in itself a finding about the gene and the disease.
inflammatory bowel disease (continued). "The study showed that LPS was identified by Toll like receptor 4 (TLR4) to release TNF-α, IL-1 beta and IL-6 and other cytokines, which mediate and promote the occurrence of inflammatory bowel disease (IBD)." (PMID 30075775, 2018). "Moreover, GDNPs are able to downregulate the TLR4/MAPK signalling pathway while synergistically increasing Nrf2 antioxidant activity to modulate immune responses and alleviate inflammatory bowel disease." (PMID 38302938, 2024). "The hypoxic environment activates the TLR4/NF-κB signaling pathway in the intestinal tissues, which is one of the contributing factors to the frequent occurrence of various intestinal diseases, including inflammatory bowel disease (IBD), in the plateau population." (PMID 39133675, 2024). "It has been reported that LPS could stimulate the TLR4-NF-κB signaling pathway to induce the release of TNF-α, IL-1β, and IL-6, which are inflammatory cytokines in inflammatory bowel disease." (PMID 37125181, 2023). "Recently, the role of toll-like receptor 4 (TLR4) signaling, which recognizes lipopolysaccharide on gram-negative bacteria, has been highlighted not only in the pathogenesis of NEC, but also in intestinal inflammation and inflammatory bowel disease." (PMID 35927380, 2022). "In addition, TLR-4 has been proven to activate the NLRP3 inflammasome signaling pathway, which represents the cornerstone of the pathophysiology of inflammatory bowel diseases." (PMID 35631426, 2022). "So far, polymorphisms in TLR4 and TLR5 have been associated with Inflammatory Bowel disease (IBD) in German Shepherd dogs (GSD), but only protective SNPs from TLR5 have been associated with IBD in other 38 dog breeds There is therefore great interest in the characterization of canine TLRs." (PMID 26401328, 2014). "In inflammatory bowel disease, activated DCs could release the inflammatory cytokines such as IL-6, IL-12 and tumor necrosis factor (TNF-α) by up-regulating the pattern recognition receptors [Toll-like receptor (TLR) 2 and TLR4], MHC class II molecules, and costimulatory molecules (CD40 and CD86)." (PMID 37670381, 2023). "Cario and Podolsky analysed TLR2, TLR3, TLR4, and TLR5 protein levels in colonic biopsies and found that TLR4 protein levels were higher in both the inflamed and the noninflamed colonic mucosa of patients with inflammatory bowel disease compared to controls." (PMID 28246611, 2017).
Arthritis (113 papers, 2005 to 2026). Inflammation of a joint. "LPS derived from bacteria had been demonstrated to cause arthritis and chronic inflammatory disorders via the TLR-4/NF-κB signaling pathway." (PMID 37016458, 2023). "Though TLR4 is normally thought to play a pathogenic role in diseases, the impacts of TLR4 on the progression of arthritis in STA model are inconsistent in different studies." (PMID 34950033, 2021). "TLR4 is expressed on primary sensory neurons and is implicated as a potential target in the treatment of pain during arthritis and OA pain in particular." (PMID 32854769, 2020). "Together, these observations suggest an essential role for TLR4 in the induction of intestinal LP IL-17 production associated with extra-intestinal IL-17 levels and the development of arthritis in IL1rn−/− mice." (PMID 28645307, 2017). "Several studies have shown that TLR4 deficiency and systemic inhibition of TLR4 using specific antagonists or neutralizing antibodies can suppress experimental arthritis." (PMID 28645307, 2017). "We show that the aberrant microbiota in IL1rn−/− mice have the capacity to enhance LP Th17 cells which are associated with arthritis, likely via TLR4-induced production of IL-1β, IL-6, and IL-23." (PMID 28645307, 2017). "We also examined the role of TLR4 in the intestinal mucosal immune responses associated with arthritis." (PMID 28645307, 2017). "Tenascin-C was initially identified as a toll-like receptor 4 (TLR4) agonist that mediates the sustained local inflammatory response associated with arthritic joint disease." (PMID 29137117, 2017). "The severity of arthritis was reduced in the TLR4 deficient mice compared to wild type littermates (mean maximum score 2,54 vs. 6,25)." (PMID 21858160, 2011). "This suppressive effect of TLR4 deficiency became obvious approximately 2 weeks after arthritis onset and was sustained in the chronic phase up to the end of the observational period of 90 days." (PMID 21858160, 2011). "We generated TLR4 deficient DBA1J mice by backcrossing the TLR4 mutation present in C3H/HeJ strain onto the DBA1J strain and investigated the course of collagen-induced arthritis in TLR4 deficient mice in comparison to wild type littermates." (PMID 21858160, 2011). "Here we show that TLR4 deficient DBA mice develop collagen induced arthritis with lower incidence and decreased severity, thereby supporting a role for TLR4 in autoimmune arthritis." (PMID 21858160, 2011). "The incidence of collagen- induced arthritis was significantly lower in TLR4 deficient compared to wild type mice (59 percent vs. 100 percent)." (PMID 21858160, 2011). "In addition, mice with gene deletions of tlr4 or loss-of-function mutations were protected from experimental arthritis." (PMID 35292659, 2022). "Importantly, TLR2 and TLR4 are crucial for autoantibody generation in lupus and a TLR4-deficient arthritis model shows attenuated disease and lower titers of autoantibodies." (PMID 34381449, 2021). "Moreover, TLR4*AA/CD14*TT was significantly associated with arthritis occurrence in SLE patients (p = 0.01 after adjustment with age of onset and gender)." (PMID 24252506, 2013). "However, the LPS receptor TLR4, has been linked to animal models of arthritis, perhaps because of the activation of TLR4 by endogenous ligands, such as Tenascin-C." (PMID 22551352, 2012). "Moreover, mice deficient in TLR4 have markedly lower numbers of Th17 cells and a reduced capacity to produce IL-17 in an experimental model of arthritis." (PMID 20169058, 2010). "In a similar model, a global deletion of TLR4 attenuated the post-inflammatory allodynia in males, whereas an intrathecal injection of a TLR4 antagonist given during the inflammatory phase fully reversed the pain-like behavior associated with arthritis in males." (PMID 39439003, 2024).
Arthritis (continued). "The importance of TLR4-signaling in the propagation of joint inflammation and destruction in RA has been highlighted by in vivo studies demonstrating that TLR4-deficient mice or antibodies blocking TLR4-signaling exhibited less severe symptoms in collagen induced arthritis than control mice." (PMID 32047494, 2019). "Further supporting the role of this receptor in the development of RA are studies showing that mice deficient in TLR4 are protected from developing experimentally induced arthritis, and that blocking the TLR4 receptor is a successful therapeutic in treating experimentally induced arthritis." (PMID 27906035, 2016). "Validation of these associations would be crucial in confirming any association of TLR4 with psoriasis and/or psoriatic arthritis with particular focus given to accurate phenotyping; including of age of onset and associated presence or absence (confirmed by a rheumatologist) of arthritis." (PMID 26830904, 2016). "However, reduced anti-CCP antibody response might be a consequence of otherwise suppressed arthritis in TLR4 deficient mice." (PMID 21858160, 2011). "Fas-deficient mice developed arthritis that was less severe, probably through a reduced IL-1R1/Toll-like receptor-4 signaling that might contribute to a decreased expression of other cytokines, chemokines and matrix metalloproteinases potentially regulated by this pathway." (PMID 15987490, 2005). "Our study indicates that Rh2-pre Exo can suppress TLR4/Myd88/NF-κB inflammatory signaling, reprogramming macrophages to an anti-inflammatory state and thereby alleviating arthritis in CIA mice." (PMID 40502627, 2025). "Arthritis does not develop in IL-1-RA-deficient mice raised in a sterile environment; however, after recolonization with Lactobacillus, these mice develop severe Th17- and TLR4-dependent arthritis." (PMID 40868558, 2025). "LPS activates TLR4 and the NF-κB pathway, triggering inflammation and activating the complement alternative pathway, which contributes to arthritis." (PMID 41019075, 2025). "We reproduced prior results demonstrating the development of maximal clinical signs (arthritis scores) between days 5 and 20 for male and female wild type (WT) and Tlr4−/− mice." (PMID 39696684, 2024). "This study constructs new engineered exosomes that can efficiently deliver therapeutic contents to pro‐inflammatory macrophages mainly through TLR4‐mediated endocytosis, thereby ameliorating the severity of arthritis in vivo." (PMID 38083984, 2024). "In the same study, using conditional DRG nociceptor TLR4 knockout animals demonstrated that HMGB1 mediates arthritis pain through TLR4 signaling in both sexes." (PMID 39439003, 2024). "One proposed mechanism of action shows that ingested HA binds to toll-like receptor-4 and promotes the expressions of interleukin-10 and cytokine signaling, which both lead to anti-inflammation of arthritis." (PMID 38731044, 2024). "As WT mice displayed an increase in spinal cord microglial immunoreactivity, we sought to measure TLR4 activation using flow cytometry in spinal microglia during the post-inflammatory phase of K/BxN arthritis." (PMID 39696684, 2024). "In recent years, it has been demonstrated that the TLR2/TLR4-NF-κB signaling pathway can be exploited as a target to reduce TLR2/TLR4 protein expression levels to cure gouty arthritis symptoms." (PMID 38652726, 2024). "We assessed the role of TLR4 on allodynia, bone remodeling and afferent sprouting in this model of arthritis." (PMID 39696684, 2024). "The top pathways specifically enriched with mice having arthritis were inflammatory and immune response, whereas other major pathways include neutrophil chemotaxis, TLR4, NOD-like, MAPK, NF-κb signaling pathways, etc.." (PMID 37396347, 2023). "Multiple studies have found that puerarin attenuates inflammation and oxidation in mice with collagen antibody-induced arthritis through the TLR4/NF-κB signaling pathway." (PMID 37033930, 2023).
Arthritis (continued). "Together, our study demonstrates the important aspects of sex and cellular location in the contribution of peripheral HMGB1 and TLR4 to arthritis-induced pain." (PMID 32796317, 2021). "In another study, mice deprived of the normal Toll-like receptor 4(TLR4)—the lipopolysaccharide (LPS) sensor—were less likely to develop arthritis." (PMID 33800376, 2021). "In the TNF-α-stimulated SFs, a significantly lower expression of NLRP3 and TLR4 was observed in the RA group, compared with the other tested forms of arthritis." (PMID 35126351, 2021). "Among TLRs, TLR4 activation would be more involved in CFA-induced arthritis rats, making the AIA model a good choice to test the anti-arthritic effect of TAK-242." (PMID 31973752, 2020). "When TLR4 is activated, it can coordinate multiple signaling cascades, including arthritis animal models and in patients with gout." (PMID 33488933, 2020). "One proposed mechanism of action shows that ingested HA binds to Toll-like receptor-4 and promotes the expressions of interleukin-10 and cytokine signalling, which both lead to anti-inflammation of arthritis." (PMID 32650511, 2020). "We found that a similar severity of arthritis is developed in LPS‐resistant TLR4−/− mice and LPS‐responder control mice." (PMID 32994999, 2020). "We suggest that molecular mechanisms, including different immune cell types, TLR4-dependent/or independent pathways, and inflammatory cytokines, contribute to the sex-related differences in arthritis-induced pain in animal models." (PMID 33114670, 2020). "In murine arthritis models, deficiencies in TLR4 and TLR2 inflicted divergent results, with TLR2 showing disease-mitigating effects, while TLR4 stimulation triggered arthritis." (PMID 31266174, 2019). "In particular, palmitic acid upregulated IL-6 in human chondrocytes and fibroblast-like synovial cells via TLR4 signaling in an arthritis model." (PMID 29097726, 2017). "We further identify a role for TLR4 activation in the intestinal lamina propria production of IL-17 and cytokines involved in Th17 differentiation preceding the onset of arthritis." (PMID 28645307, 2017). "We also provide evidence that tobramycin-sensitive indigenous commensal intestinal bacteria contribute to arthritis in IL1rn−/− mice and identify a significant role for TLR4 in mucosal induction of IL-1β and IL-17 prior to the onset of arthritis." (PMID 28645307, 2017). "This is in agreement with our previous study showing that TLR4 induces systemic and local IL-17 production and promotes arthritis in IL1rn−/− mice." (PMID 28645307, 2017). "A proinflammatory role for TLR4 during arthritis has previously been widely attributed to TLR4 activation by endogenous damage-associated molecular patterns present in the joint rather than microbial agonists." (PMID 28645307, 2017). "We also showed that IL1rn−/− arthritis is dependent on the activation of Toll-like receptor 4 (TLR4), which affected systemic Th17 cell differentiation." (PMID 28645307, 2017). "Considering differential roles of TLR2 and TLR4 in IL1rn−/− arthritis, we sequenced samples of IL1rn−/−Tlr2−/− and IL1rn−/−Tlr4−/− mice in parallel." (PMID 28645307, 2017). "The arthritis phenotype in IL1rn−/− mice was previously shown to depend on Toll-like receptor 4 (TLR4)." (PMID 28645307, 2017). "These discrepancies demonstrate that the impact of TLR4 on arthritis development in the K/BxN STA model varies from study to study and that further studies are therefore needed to clarify its role." (PMID 27313578, 2016). "Activation of spinal TLR4 also plays a critical role in the transition from acute to chronic post-inflammatory mechanical hypersensitivity in arthritis." (PMID 25571780, 2015). "An earlier study on experimental arthritis had noted that Pglyrp-2 promoted arthritis by supporting local induction of pro-inflammatory chemokines and cytokines in a TLR4 dependent manner." (PMID 26332373, 2015).
Arthritis (continued). "Compared to wild type (WT) mice, TLR4-/- mice showed attenuated arthritis and low interferon (IFN)-γ, IL-12p35 and IL-1β transcript levels in the joints, but high transforming growth factor (TGF)-β expression." (PMID 23036692, 2012). "Despite that several studies report a functional link between TLR4 and interleukin-(IL-)1β in arthritis, TLR4-mediated regulation of the complicated cytokine network in arthritis is poorly understood." (PMID 23036692, 2012). "Gr-1+ cell-depleted spleen cells partially restored joint inflammation, indicating that Gr-1+ cells partly contribute to the TLR4-mediated pathogenesis of arthritis." (PMID 23036692, 2012). "First, TLR4-/- mice produce minimal amounts of IL-12p35 in their joints during antibody-induced arthritis compared with WT mice." (PMID 23036692, 2012). "Several studies have demonstrated the crucial role of TLR4 in the pathogenesis of RA in murine arthritis models." (PMID 23036692, 2012). "Injection of recombinant IFN-γ, IL-12 or IL-1β into TLR4-/- mice restored arthritis as compared to WT mice, indicating that these pro-inflammatory cytokines contribute to the pathogenesis of TLR4-mediated joint inflammation in antibody-induced arthritis." (PMID 23036692, 2012). "It has been suggested that TLR4-mediated signals promote joint inflammation by increasing levels of either IL-17 or IL-1β in murine arthritis models." (PMID 23036692, 2012). "Most studies of murine experimental arthritis have suggested a contribution from TLR4 to the maintenance of inflammation." (PMID 22691272, 2012). "Next, to confirm the function of macrophages and mast cells in TLR4-mediated regulation of arthritis, we transferred macrophages and mast cells from WT or TLR4-/- mice into macrophage- and mast cell-depleted WT mice, respectively." (PMID 23036692, 2012). "To explore the mechanism by which TLR4 signals promote antibody-induced arthritis, we measured mRNA expression of various cytokines in the joint tissues of TLR4-/- and WT mice, some of which had been injected with LPS, 10 days after K/BxN serum transfer." (PMID 23036692, 2012). "To confirm the functional involvement of individual cytokines in TLR4-mediated arthritis, we injected i.p. recombinant IFN-γ, IL-12 or IL-1β into TLR4-/- mice during antibody-induced arthritis." (PMID 23036692, 2012). "In that study, TLR2−/− mice had reduced FoxP3 expression, greater IL-17 expression, and increase arthritis severity, while TLR4−/− mice had a lesser severity of arthritis, and lowered IL-17 expression." (PMID 21695198, 2011). "Arthritis severity, as defined by the scoring method described in the M&M section, was significantly milder in TLR4 defective mice with a mean maximal score of 2,54 compared to 6,25 for the wt groups." (PMID 21858160, 2011). "For collagen-induced arthritis in this strain, a protocol with incomplete Freund's adjuvant without heat-killed mycobacteria was used in order to avoid potential TLR4 stimulation in wildtype mice by mycobacterial substances." (PMID 21858160, 2011). "TLR4 takes part in the initiation and progression of both autoantibody/lipopolysaccharide (LPS)-triggered arthritis and serum transferred arthritis." (PMID 20500834, 2010). "The intra-articular triggering of TLRs led to the joint inflammation, and TLR2 and TLR4 have been shown to play a critical role in bacterial cell wall-induced arthritis." (PMID 18847495, 2008). "Therapeutic TLR4 blockade effectively suppressed arthritis in A20myel-KO mice." (PMID 41583484, 2025). "Mice with a mutant defective TLR4 resolved faster serum transfer arthritis." (PMID 38255243, 2024). "It has also been reported that quercetin could attenuate arthritis by targeting the HMGB1/TLR4/p38/ERK1/2/NF-κB p65 pathway in mice." (PMID 38927100, 2024). "In addition, TLR4 protein was highly expressed in the gouty arthritis population, and the concentration of TLR4 protein increased as the UA levels increased in this population." (PMID 38652726, 2024).